IL6 (interleukin 6)
Diseases named in the same sentence as IL6 in open-access papers (continued):
Sharing a sentence is not in itself a finding about the gene and the disease.
rheumatoid arthritis (continued). "The blockade of IL-6 receptor by the humanized anti-IL-6 receptor antibody tocilizumab has been used in the treatment of rheumatoid arthritis, and a human anti-IL-6 monoclonal antibody, sirukumab, has been under evaluation in patients, including those with rheumatoid arthritis." (PMID 28556833, 2017). "Elevated levels of circulating IL-6 and sIL-6R, on the other hand, frequently accompany pathophysiologic conditions and constitute potential drug targets in the treatment of diseases like rheumatoid arthritis, asthma, and multiple sclerosis (3, 12, 17, –, 19)." (PMID 28265003, 2017). "However, more recent evidence from various autoimmune diseases (e.g., inflammatory bowel disease, rheumatoid arthritis) has shown that the IL-6 activity is more complex with important effects also on tissue homeostasis, regeneration, and metabolism." (PMID 28642760, 2017). "However, uncontrolled persistent production of IL-6 leads to the development of rheumatoid arthritis (RA)." (PMID 28529957, 2017). "Interleukin-6 (IL-6) is one of several pro-inflammatory cytokines present at elevated levels in the synovial fluid of individuals with confirmed clinical diagnosis of rheumatoid arthritis (RA) and osteoarthritis (OA)." (PMID 29276788, 2017). "As a master regulator of pro-inflammatory cytokines such as IL-1β, IL-6 and GM-CSF, over expression of TNF-α causes a variety of chronic inflammatory diseases including rheumatoid arthritis, Crohn’s disease, psoriatic arthritis, ankylosing spondylitis and psoriasis, and so on." (PMID 27658047, 2016). "Humanized IL-6 pathway antagonists, such as tocilizumab (anti-IL-6R) have been used successfully in rheumatoid arthritis, Castleman’s disease and juvenile idiopathic arthritis, and may have a role in SIRS and CRS." (PMID 31557985, 2016). "In addition, pioglitazone treatment modestly ameliorates rheumatoid arthritis (RA) activity by preventing bone loss and suppresses plasma levels of cytokines, including TNF-α, IL-1β, and IL-6." (PMID 27548145, 2016). "Additionally, dysregulation of IL-6 production plays a role in chronic autoimmune diseases such as rheumatoid arthritis." (PMID 31557985, 2016). "Studies have pointed out a key role of IL-6 in the pathophysiology of rheumatoid arthritis." (PMID 27819273, 2016). "Indeed, in chronic inflammatory autoimmune diseases such as rheumatoid arthritis, in which the production of IL-6 is deregulated, the circulating lipid levels (total cholesterol and triglycerides) are increased while blockade of IL-6 decreases their levels." (PMID 27333268, 2016). "Moreover, inflammatory mediators such as prostaglandin E2 and inflammatory cytokines (TNF-α, Il-6) have been shown to exacerbate the related pain and decrease in mobility or physical activity in patients with rheumatoid arthritis and other joint diseases." (PMID 27333300, 2016). "IL-6 is also involved in the pathophysiology of rheumatoid arthritis and multiple sclerosis." (PMID 27128729, 2016). "Thus, the markedly elevated level of IL-6 in rheumatoid arthritis and osteoarthritis sera and synovial fluid would be expected to generate significant MMP-9 to cause the degradation of articular cartilage extracellular matrix proteins." (PMID 27398263, 2016). "In vivo, a pomegranate extract diet rich in ellagitannins has been acknowledged to suppress inflammation by decreasing the IL-6 level in the joints of collagen-induced arthritis in mice, while the consumption of pomegranate decreases oxidative status in patients with rheumatoid arthritis." (PMID 26569295, 2015). "Interleukin-6 (IL-6) cytokine signaling is key in Rheumatoid Arthritis (RA) pathophysiology." (PMID 26336855, 2015). "For example, IL-6 overexpression is involved in rheumatoid arthritis." (PMID 26471417, 2015). "Moreover, Wnt5a overproduction in rheumatoid arthritis was related to the secretion of IL-1β and IL-6 in BMSC." (PMID 24993819, 2014).
rheumatoid arthritis (continued). "Moreover, IL-6 is detected in high levels in disease conditions including autoimmune disease, such as rheumatoid arthritis, atherosclerosis, diabetes, and inflammatory-bowel diseases." (PMID 24729663, 2014). "Moreover, nicotine inhibits TNF-α-induced IL-6 and IL-8 secretion in fibroblast-like synoviocytes from patients with rheumatoid arthritis." (PMID 25479074, 2014). "IL-6 is a proinflammatory cytokine up-regulated in chronic inflammatory diseases like inflammatory bowel disease (IBD), and a monoclonal antibody against IL-6 (tocilizumab) is used in patients with rheumatoid arthritis and in clinical studies for the treatment of IBD." (PMID 24710357, 2014). "Inflammatory mediators such as Interleukin 6 (IL-6) and (MIP-1α) have been associated with osteoarthritis (OA) and rheumatoid arthritis (RA) and accordingly NSAIDs are often prescribed, however with considerable adverse effects, such as damage to gastrointestinal mucosa." (PMID 25019344, 2014). "Tocilizumab is a humanized monoclonal antibody which specifically inhibits IL-6 by competitively blocking the binding site to the IL-6 receptor, definitely approved for patients with rheumatoid arthritis refractory to traditional disease-modifying antirheumatic drugs." (PMID 25061259, 2014). "IL-6 is an inflammatory cytokine that plays an important role in the development of Th17 cells and contributes to a number of autoimmune diseases, including rheumatoid arthritis." (PMID 25478789, 2014). "The increased productions of IL-1β and IL-18 induce renal inflammation and diseases, and excessive IL-6 expression promotes the development and progression of chronic inflammatory diseases, such as, cardiovascular diseases, Alzheimer’s disease, rheumatoid arthritis, and CKD." (PMID 23922826, 2013). "Treatment with tocilizumab blocks interkeukin-6 (IL-6) signaling within inflammatory and immune cells, and improves the clinical symptoms of autoimmune diseases, such as rheumatoid arthritis (RA), juvenile idiopathic arthritis (JIA) and multicentric Castleman's disease (MCD)." (PMID 23936360, 2013). "Similarly, altered IL-6 production has been found in inflammatory states such as rheumatoid arthritis, CD and UC." (PMID 24046362, 2013). "In addition, the overexpression of IL-6 is involved in physiological conditions such as rheumatoid arthritis." (PMID 23573152, 2013). "On the contrary, however, blocking the action of IL-6 in rheumatoid arthritis patients led to enhanced plasma glucose levels, and IL-6 infusion acutely increased insulin-stimulated glucose disposal in humans, probably via AMP-activated protein kinase in skeletal muscles." (PMID 22615828, 2012). "Similarly, in group 2, which mainly consisted of HuGE-pathways, IL-6 and IL-10 signaling pathways were observed and found to be connected through the pathway “role of macrophages, fibroblasts and endothelial cells in Rheumatoid Arthritis”." (PMID 21390307, 2011). "Further, Avemar decreased inflammation through other immunomodulatory mechanisms, such as decreased production of pro-inflammatory cytokines IL-6 and IL-10 in mice with systemic lupus erythematosus and decreased macrophage infiltration in animal models of rheumatoid arthritis." (PMID 19622599, 2011). "In addition, H2S also inhibits IL-6 secretion of fibroblasts isolated from the synovial membrane of rheumatoid arthritis patients." (PMID 21779360, 2011). "IL-6 is a therapeutic target in juvenile idiopathic arthritis and rheumatoid arthritis in humans." (PMID 19640302, 2009). "In many chronic inflammatory diseases, including chronic inflammatory bowel disease, peritonitis, rheumatoid arthritis, asthma, as well as colon cancer, IL-6 trans-signalling promotes transition from acute to chronic inflammation and thereby aids in the maintenance of a disease state." (PMID 19698101, 2009).
rheumatoid arthritis (continued). "Production of TNF-α, IL-6, IL-8, histamine and other inflammatory mediators by the activated mast cells could drive synovitis in RA, and it has been shown that mice deficient in mast cell activation were resistant to the induction of arthritis in the K/BXN model of rheumatoid arthritis." (PMID 19133134, 2009). "Adrenomedullin may thus be useful as a treatment for rheumatoid arthritis; however, the effect of adrenomedullin on IL-6 production in the synovial tissue may be an undesirable adverse effect in rheumatoid arthritis therapy." (PMID 19014513, 2008). "Leukaemia inhibitory factor, inducible through IL-1β and loaded on the same component together with IL-1β and IL-10, has been shown to have parallels with IL-1, tumour necrosis factor-α and IL-6 within the context of promoting inflammation in rheumatoid arthritis." (PMID 18289371, 2008). "Subgroup analysis revealed that in rheumatoid arthritis (RA) patients, the probiotics group showed greater improvements in IL-6, IL-1β, and TNFα compared to the controls." (PMID 41978157, 2026). "Rheumatoid arthritis: Six inflammatory factors, including Neurturin, Interleukin-6, Programmed cell death 1 ligand 1, CUB domain-containing protein 1, C-C motif chemokine 4, and CD40L receptor, are significantly associated with RA." (PMID 41399369, 2026). "Analyses of the SNPs -174 G/C of the IL-6 gene and -308 G/A of the TNFα gene have been described as important factors capable of influencing the pathogenesis of rheumatoid arthritis (RA)." (PMID 41472214, 2025). "Rheumatoid arthritis (RA): The increased levels of IL-1β, TNFα, and IL-6 which are found in RA also resemble a Trained Immunity phenotype." (PMID 41432375, 2025). "Individuals diagnosed with rheumatoid arthritis frequently report morning joint stiffness, a symptom that has been correlated with elevated circulating levels of pro-inflammatory cytokines such as tumor necrosis factor and interleukin-6 during the early morning hours." (PMID 40559115, 2025). "miR-451a was previously reported to be implicated in inflammatory pathways via upregulating in rheumatoid arthritis and systemic lupus erythematosus (SLE) and downregulating in influenza-infected dendritic cells which led to the increased secretion of inflammatory cytokines, e.g., IL6 and TNFα." (PMID 39934489, 2025). "Tocilizumab (TCZ) is a monoclonal antibody that neutralizes interleukin (IL)-6 and is indicated for diseases characterized by markedly elevated inflammatory markers, such as rheumatoid arthritis (RA)." (PMID 39949771, 2025). "Rheumatoid arthritis (RA) is characterized by chronic inflammation driven by pro-inflammatory cytokines such as interleukin-6 (IL-6) and interferon-gamma (IFN-γ), which activate intracellular JAKs through immune cell receptors." (PMID 40677425, 2025). "Interleukin-6 (IL-6) plays an important role in the pathogenesis, progression, and severity of rheumatoid arthritis (RA)." (PMID 41280923, 2025). "Under inflammatory conditions in rheumatoid arthritis (RA), several molecules such as IL-1β, IL-6, TNF-α, IL-17, and hypoxia-inducible factor-1α (HIF-1α) are produced, which can mediate bone loss." (PMID 40153574, 2025). "Several of the induced genes, particularly proinflammatory cytokines IL1β, IL6, and PTGS2 and genes involved in antigen presentation (HLA-DRB1), have been implicated in persistent inflammation in other conditions including atopic dermatitis, psoriasis, and rheumatoid arthritis." (PMID 41333458, 2025). "Furthermore, recognizing that queuine analogs might also influence non-immune cell types, researchers screened these compounds in rheumatoid arthritis synovial fibroblasts by measuring IL-6 secretion, followed by validation in EAE models." (PMID 41357216, 2025). "Among the most widely used are IL-6 inhibitors, such as tocilizumab and sarilumab, which have demonstrated clinical efficacy in rheumatoid arthritis (RA), systemic juvenile idiopathic arthritis, and giant cell arteritis." (PMID 41041324, 2025).
rheumatoid arthritis (continued). "The gene encoding pro-inflammatory cytokines such as IL-1, IL-2, IL-6, Tumor necrosis factor (TNF)-α, and Monocyte chemoattractant protein (MCP)-1 play significant roles in increasing the risk of chronic diseases such as asthma, atherosclerosis, and rheumatoid arthritis." (PMID 38164478, 2024). "However, the autoimmune progression in rheumatoid arthritis can lead to cachexia and severe psychiatric issues, and anti-IL-6 therapy has shown efficacy in treating affected joints, alleviating extra-articular manifestations, stabilising lung fibrosis, and reducing cachexia." (PMID 39676864, 2024). "Compared to other cytokines such as interleukin-1 (IL-1) and tumor necrosis factor (TNF), anti-IL-6 therapy is more effective in improving serum lipoprotein levels in patients with rheumatoid arthritis (RA)." (PMID 39749325, 2024). "IL-6 contributes to other inflammatory pathologies like rheumatoid arthritis (RA), multiple sclerosis (MS), asthma, cancer, metabolic syndrome, type 2 diabetes, and inflammatory bowel disease (IBD)." (PMID 38840141, 2024). "Moreover, prolactin induces the phosphorylation and activation of the signal transducer and activator of transcription-3 (STAT3), resulting in the downregulation of the osteoclast differentiation induced by proinflammatory cytokines, like IL-1β and IL-6, and rheumatoid arthritis (RA)." (PMID 38338751, 2024). "Blockade of IL-6 helps normalize previously upregulated CYP enzyme activity due to chronic inflammation, and DDIs involving CYP substrates and IL-6 inhibitors may therefore be flagged by databases in the context of chronic inflammatory states such as rheumatoid arthritis." (PMID 37368815, 2023). "Additionally, IL-6 affects T cells by enhancing overreactive Th1 activity, the mechanism responsible for the induction of several organ-specific autoimmune inflammatory diseases, such as multiple sclerosis, rheumatoid arthritis and T1DM." (PMID 37025699, 2023). "Thus, targeting IL-6 and/or TNFα offers approaches to the diagnosis and treatment of different primary diseases (e.g., rheumatoid arthritis and sarcopenia) and health-compromising secondary conditions (e.g., cancer cachexia and post-infectious acute respiratory distress syndrome, ARDS)." (PMID 36830664, 2023). "We previously observed protein expression of CCL28 and CCR10 to be upregulated by LPS and pro-inflammatory cytokines such as TNF-α and IL-6 in monocytes and macrophages isolated from patients with rheumatoid arthritis (RA)." (PMID 36713846, 2023). "S100A11 has been reported to stimulate the production of the pro-inflammatory cytokine IL-6 by peripheral blood mononuclear cells (PBMC) and overexpression of S100A11 was associated with inflammation-related health problems such as osteoarthritis or rheumatoid arthritis." (PMID 36720844, 2023). "Patients with rheumatoid arthritis (RA) are prone to muscle atrophy due to inflammatory cytokines such as tumor necrosis factor α (TNFα) and interleukin 6 (IL-6)." (PMID 37041556, 2023). "Anti-IL-6 agents have shown potential benefits in inflammatory disorders, but safety concerns, such as gastrointestinal perforations, have been raised based on previous studies with tocilizumab (a monoclonal antibody against IL-6R) in rheumatoid arthritis patients." (PMID 37626745, 2023). "Since IL-6 is a key cytokine in the pathogenesis of rheumatoid arthritis, its effect on osteoblasts of RA patients was investigated initially." (PMID 37280473, 2023). "The serum level of IFN-λ1 has also been found to increase in rheumatoid arthritis (RA) patients, and the pro-inflammatory cytokines like IL-6 and IL-8 are further increased in synovial fibroblasts after IFN-λ1 application." (PMID 37809098, 2023).
rheumatoid arthritis (continued). "Notably, high serum IL-6 concentrations have been associated with non-response to rituximab in rheumatoid arthritis." (PMID 36756239, 2023). "Targeting the IL-6-signalling pathway in rheumatoid arthritis (RA) patients with the use of the monoclonal antibody, tocilizumab, is analgesic." (PMID 37484030, 2023). "In other conditions, including rheumatoid arthritis (RA) and Castleman disease, both serum IL-6 and sIL-6R increase in patients after administration of tocilizumab while the disease symptoms ameliorates." (PMID 37215114, 2023). "Increases in the IL-6 level are known to be related to the occurrence of many autoimmune and inflammatory diseases, such as rheumatoid arthritis (RA), juvenile idiopathic arthritis (JIA) and Castleman’s disease." (PMID 36902507, 2023). "Noteworthy examples include tumor necrosis factor-alpha (TNF-α), interleukin-1 beta (IL-1β), and IL-6, which are often elevated in disorders like rheumatoid arthritis (RA), intensifying inflammation and contributing to tissue damage." (PMID 37965323, 2023). "When tocilizumab is not available, sarilumab, a human monoclonal antibody targeting IL-6 soluble receptors, which is already approved for rheumatoid arthritis (RA) treatment, represents a valid alternative for IL-6 blockade." (PMID 35645219, 2022). "In murine arthritis, tofacitinib reduces levels of plasma IL-6 and CXCL10 (IFN-γ–induced protein 10), while in rheumatoid arthritis (RA), it lowered IL-6 in one clinical trial but decreased CXCL10 in another." (PMID 35943798, 2022). "In rheumatoid arthritis (RA), the expression of TLRs signaling pathway can be used as the activation pathway of IL-6." (PMID 36506506, 2022). "In addition, IL-6 may be a therapeutic target, and IL-6 inhibitors have already been approved for the treatment of several disorders, including for rheumatoid arthritis." (PMID 35039091, 2022). "In the autoimmune disease rheumatoid arthritis (RA), for example, electrical stimulation reduced inflammatory cytokines in rat models of interleukin (IL) 1, 2, and IL6 and tumour necrosis factor (TNF)." (PMID 35955708, 2022). "IL-6 and its secreted receptor sIL-6Rα are increasingly recognized as master cytokines, upstream of a wide array of inflammatory processes, including pathologies as diverse as cytokine release syndrome, acute allograft rejection, rheumatoid arthritis, asbestosis and cachexia." (PMID 35222439, 2022). "Patients with EO-rheumatoid arthritis (EO-RA) have higher serum interleukin-6 levels and lower serum TNFα levels than patients with NEO-RA, and high levels of TNFα are associated with higher risk of hospitalization and death." (PMID 35351986, 2022). "A cross-sectional design of rheumatoid arthritis (RA) patients found that serum levels of NPY are significantly related to TNF-α levels and disease activity in RA independently of IL-6, TNF-α, or leptin levels." (PMID 35273572, 2022). "Elevated ERK1/2 activity has been found in inflamed joints of patients with the autoimmune disease rheumatoid arthritis (RA) and ERK1/2 inhibitors show therapeutic promise by reducing levels of RA-associated inflammatory cytokines including TNF, IL-1 and IL-6." (PMID 36281999, 2022). "Furthermore, elevated adiponectin promotes IL-6 and IL-8 secretion in Rheumatoid Arthritis (RA)." (PMID 36158216, 2022). "Another clinical study investigated the efficiency of an anti-IL-6 treatment, tocilizumab, on endothelial function in high-risk CVD patients with rheumatoid arthritis (RA)." (PMID 35600479, 2022). "Currently, anti-IL-6 or IL-6R therapy is used worldwide in various autoimmune diseases, such as rheumatoid arthritis (RA), juvenile idiopathic arthritis (JIA), systemic sclerosis, and uveitis." (PMID 33816637, 2021). "Tocilizumab [TCZ, (Roche Pharma (Schweiz) Ltd., S20171024)], a human monoclonal antibody directed against IL-6, has been commonly used in the therapy of rheumatoid arthritis (RA)." (PMID 33937333, 2021).